BTK (Bruton tyrosine kinase)
Diseases named in the same sentence as BTK in open-access papers (continued):
Sharing a sentence is not in itself a finding about the gene and the disease.
autoimmune disease (continued). "Furthermore, the finding that BTK levels of B cells are elevated in various autoimmune diseases, and BTK overexpressing is associated with breaching tolerance and development of autoimmunity, makes BTK a potential therapeutic target." (PMID 34068035, 2021). "NX‐5948 specifically targets BTK protein degradation, with indications expanded to B‐cell malignancies and autoimmune diseases, reflecting BTK PROTAC application potential across different disease areas." (PMID 41049269, 2025). "Expanding knowledge of BTK's immunomodulatory role has driven the development of BTK inhibitors (BTKi) for B‐cell malignancies and autoimmune diseases." (PMID 40222822, 2025). "Inhibition of BTK, especially in autoimmune disorders, has the potential to decrease Fcy receptor‐mediated macrophage function and reduce autoantibody production." (PMID 39973148, 2025). "A highly selective covalent BTK inhibitor, evobrutinib, has been discovered for the treatment of autoimmune disorders, including SLE." (PMID 39518015, 2024). "Although BTK inhibitors show potential in treating autoimmune diseases, the clinical outcomes have been mixed due to challenges in efficacy and safety." (PMID 39676874, 2024). "Bruton tyrosine kinase (BTK) plays a significant role in the pathophysiology of autoimmune diseases and inflammation." (PMID 38947690, 2024). "Although several BTK inhibitors have been discovered for the treatment of autoimmune diseases, acquired resistance and toxicities limit their effectiveness." (PMID 39500878, 2024). "To date, BTK inhibitors (BTKis) have revolutionized the treatment landscape of multiple hematological malignancies, solid tumors, and, more recently, autoimmune disorders." (PMID 38396884, 2024). "Downregulation or constitutive activation of BTK is reported in patients with autoimmune diseases or various B-cell leukemias." (PMID 38971313, 2024). "Bruton’s tyrosine kinase (BTK) inhibitors have revolutionized the landscape for the treatment of hematological malignancies, solid tumors, and, recently, autoimmune disorders." (PMID 38396884, 2024). "This broader mechanism of action presents BTK inhibitors as a promising therapeutic strategy not only for MS but also for other autoimmune diseases and B cell malignancies." (PMID 39611149, 2024). "Since the discovery of BTK in XLA, studies investigating its role in autoimmune diseases have reinforced the link between BTK and autoimmune phenomena." (PMID 39518015, 2024). "Clinical application of BTK inhibitors in inflammatory and autoimmune disease is also being actively explored." (PMID 37651403, 2023). "A decisive role has been attributed to BTK in the pathogenesis of autoimmune disorders and B-cell malignancies." (PMID 38125430, 2023). "Knowledge about the structural complementarity of BTK and its inhibitors supports the optimization of existing drugs and the discovery of drugs for implication in B-cell malignancies and autoimmune diseases." (PMID 36986499, 2023). "As BTK is an essential factor in B cell signaling, especially in autoimmune diseases, BTK inhibitors can be a potential treatment for pemphigus." (PMID 38125430, 2023). "Designing new inhibitors of BTK has been an important objective for advancing development of improved therapeutic agents against cancer and autoimmune disorders." (PMID 37651403, 2023). "The pathophysiology of several autoimmune diseases, such as pemphigus disorder, relies on the BTK signaling pathway." (PMID 38125430, 2023). "Given the role of BTK in autoimmunity, BTK-Ncovi are under preclinical trials against autoimmune disorders." (PMID 36986499, 2023). "Another aVMC (cg23501813) mapped to Bruton’s tyrosine kinase (BTK) which is a key mediator of B cell receptor signaling and is linked to age-related autoimmune diseases common in females such as rheumatoid arthritis (RA) and systemic lupus erythematosus (SLE)." (PMID 37626340, 2023).
autoimmune disease (continued). "Encouragingly, next-generation BTK inhibitors that are currently in development for chronic urticaria and autoimmune diseases are more selective for BTK with fewer off-target effects, and therefore show more favorable side effect profiles." (PMID 37384412, 2023). "Recently, the inhibition of Bruton’s tyrosine kinase (BTK) was demonstrated as a possible therapeutic option to control inflammation of autoimmune disorders by modulating the lymphocytes and innate immune cell signaling pathways." (PMID 37376420, 2023). "Covalent inhibitors of BTK, like ibrutinib and acalabrutinib, are approved for use in B-cell malignancies and autoimmune diseases." (PMID 36986499, 2023). "BTK has become a particularly attractive therapeutic target in autoimmune diseases and B-cell malignancies, making BTK inhibitors a valuable and important therapeutic option." (PMID 36969836, 2023). "It is also necessary to assess the presence of autoimmune diseases in patients before starting BTK inhibitor therapy, because the incidence of autoimmune complications is very common in lymphoid malignancies." (PMID 37845755, 2023). "In conclusion, the use of small-molecule inhibitors targeting BTK has demonstrated significant potential for treating different types of B-cell malignancies and autoimmune disorders." (PMID 38138527, 2023). "BTK inhibitors are approved for B-cell lymphoproliferative neoplasms and are increasingly studied in autoimmune disorders." (PMID 37795092, 2023). "In view of the fundamental role of BTK in autoimmune disease, this study was conducted to characterize the role of BTK in an in vitro model of GO." (PMID 36521376, 2022). "Here, we review the role of BTK in different cell signaling pathways, the development of BTKi in B-cell malignancies, and their emerging role in the treatment of MS and other autoimmune disorders." (PMID 36294458, 2022). "BTK inhibitors (BTKis) have become very important targets in the treatment of inflammatory reactions and autoimmune diseases, as well as of B-cell malignancies, including CLL." (PMID 35159041, 2022). "BTK inhibitor is of high clinical value in B-cell malignancies and has potential clinical applications in autoimmune diseases." (PMID 36003388, 2022). "As BTK is involved in B-cell and other cell signaling pathways, BTKi also appear to be promising drugs for treatment of autoimmune diseases with aberrant B-cell function such as SLE, RA, and MS." (PMID 36294458, 2022). "Selective BTK inhibitionis well viewed as a promising therapyfor multiple hematological cancers and autoimmune diseases." (PMID 36407952, 2022). "Several clinical trials have shown promising results of BTK inhibitors for treating patients with various autoimmune diseases, such as RA and multiple sclerosis (MS)." (PMID 36220996, 2022). "The increased activity of BTK has been observed in several autoimmune disorders, including SLE and RA." (PMID 35628931, 2022). "Clinical applications for BTK inhibitors continue to increase and include autoimmune diseases such as rheumatoid arthritis." (PMID 35422819, 2022). "Recent studies revealed that BTK plays a significant role in the pathogenesis of inflammatory diseases, especially autoimmune diseases." (PMID 36183125, 2022). "BTK expression level in peripheral B-cells correlates with disease severity in a variety of autoimmune diseases including rheumatoid arthritis, primary Sjogren syndrome, lupus nephritis, IgA nephropathy, and active granulomatosis with polyangiitis." (PMID 36521376, 2022). "Orelabrutinib (ICP-022, Biogen/Innocare Pharma) is an orally available, second-generation BTK inhibitor being developed for the treatment of B cell malignancies and autoimmune diseases." (PMID 35159041, 2022). "More recently, BTK inhibitors have shown promise for treating autoimmune diseases and other immune disorders in preclinical studies and early clinical trials." (PMID 35628931, 2022).
autoimmune disease (continued). "Overactivation of BTK in these cells activates multiple signaling pathways to promote the pathogenesis of inflammatory diseases, including autoimmune diseases, infections, and chronic inflammatory diseases." (PMID 36183125, 2022). "Both B cells and macrophages play critical roles in the development of various autoimmune diseases including SSc and lupus nephritis, and are both impacted by BTK activation." (PMID 35874767, 2022). "Many studies have shown that BTK inhibitors effectively ameliorate disease pathology in various animal models of autoimmune diseases." (PMID 36220996, 2022). "PI3K, IKK, and NF-κB are involved in several important signaling pathways downstream of BTK and play significant roles in the development of autoimmune diseases." (PMID 35729649, 2022). "A first-in-human healthy volunteer study confirmed poseltinib as a potential BTK inhibitor for the treatment of autoimmune diseases." (PMID 35628931, 2022). "In human autoimmune disease, increased BTK protein levels and phosphorylation were found in B cells from ACPA+ RA, SjS, and glomerulonephritis with polyangiitis (GPA) patients with active disease." (PMID 36359789, 2022). "It is unclear what threshold of BTK inhibition is required for clinical efficacy in treating autoimmune diseases and so the majority of these covalent inhibitors have included twice daily dosing regimens that achieve near complete inhibition of BTK activity." (PMID 34803999, 2021). "One promising approach are BTK inhibitors, which are so far known from and approved for the treatment of different B cell malignancies and some autoimmune diseases." (PMID 33880738, 2021). "In recent years, the use of novel BTK inhibitors was extended to autoimmune diseases such as RA and SLE." (PMID 33880738, 2021). "Most of them mainly described the development of BTK inhibitors in treating RA or discussed the validity of BTK inhibition in autoimmune diseases." (PMID 34443496, 2021). "The BTK inhibitors discussed in this paper that are being tested in the clinic to treat autoimmune diseases and if approved, will be the first in class drugs for treating these diseases." (PMID 34803999, 2021). "While still in the middle of their clinical development for treating autoimmune diseases, results from some of the most selective BTK inhibitors look promising as mild to moderate safety events are most commonly reported." (PMID 34803999, 2021). "In summary, these data suggest that BTK has become an important target for innate immune regulation, and that limiting BTK activity is essential for preventing autoimmune diseases." (PMID 33389462, 2021). "In this report, we assessed key topic areas affecting the successful clinical development of BTK inhibitors in autoimmune diseases." (PMID 34803999, 2021). "Collectively, the new class of BTK inhibitors show promise in bringing new treatment paradigms to treating autoimmune disease disorders." (PMID 34803999, 2021). "BTK inhibition also led to positive outcomes in some other autoimmune diseases, including urticaria (NCT03137069), immune thrombocytopenia (ITP) (NCT04562766), pemphigus (NCT03762265), and IgG4-related disease (RD) (NCT04520451)." (PMID 34443496, 2021). "This review will cover recent advances in the field of medicinal chemistry towards small-molecule BTK inhibitors under clinical trials for the treatment of inflammatory and autoimmune diseases, including RA, SS, MS, SLE, urticaria, pemphigus, ITP, and RD." (PMID 34443496, 2021). "Poseltinib was confirmed as a potential BTK inhibitor for the treatment of autoimmune diseases and now we are exploring the possibility for further indication expansion such as multiple sclerosis." (PMID 34548595, 2021). "Further experiments with mature B cells using BTK inhibitors demonstrated the involvement of BTK in B cell malignancies and models of autoimmune diseases." (PMID 34685540, 2021).
autoimmune disease (continued). "For over a decade, there have been great efforts devoted to developing BTK inhibitors for potential clinical application in chronic inflammatory diseases and autoimmune diseases, in addition to hematologic malignancies." (PMID 34443496, 2021). "Given the central role of BTK in immunity, BTK inhibition represents a promising therapeutic approach for the treatment of inflammatory and autoimmune diseases." (PMID 34443496, 2021). "BTK inhibitors have been developed to treat B-cell malignancies and autoimmune diseases including multiple sclerosis (MS), where it is postulated that inhibiting BTK blocks the maturation of B cells." (PMID 39355638, 2021). "As a key modulator downstream of B cell receptor signalling pathway, Bruton’s tyrosine kinase (BTK) is emerging as a promising drug target in B cell malignancies and autoimmune disorders." (PMID 33627128, 2021). "Ibrutinib is a first-generation Bruton's tyrosine kinase (BTK) inhibitor that has shown efficacy in autoimmune diseases and has consequently been developed as a positron emission tomography (PET) radiotracer." (PMID 39355638, 2021). "The discovery of the essential roles that BTK plays in B cell development, trafficking, and antibody production has opened a new area for treating autoimmune disorders." (PMID 34803999, 2021). "BTK inhibitors offer a new paradigm for the treatment of autoimmune diseases and AIBD in particular, with pemphigus having the most compelling unmet need, since they potentially act much faster via the innate immune system, compared with rituximab." (PMID 34447768, 2021). "Small-molecule BTK inhibitors have great potential as therapeutics to treat inflammatory or autoimmune diseases and as tools to probe the biology of BTK." (PMID 34443496, 2021). "Bruton’s tyrosine kinase (BTK) inhibitors initially were introduced to the market for oncology and now are finding their way into fighting autoimmune diseases." (PMID 33802091, 2021). "One example of this relationship is between CXCL12 as a driver of autoimmune diseases and its role in activating BTK as part of the chemotaxis process." (PMID 34803999, 2021). "Great efforts have been made in developing BTK inhibitors for potential clinical applications in inflammatory and autoimmune diseases." (PMID 34443496, 2021). "Together, these studies demonstrate that elevated BTK levels are a characteristic of B cells across different autoimmune diseases." (PMID 34068035, 2021). "BTK in B cells is of considerable interest as a drug target in autoimmune diseases such as rheumatoid arthritis due to its role in regulating immune tolerance." (PMID 34548595, 2021). "BTK inhibitors are promising novel agents that have potential efficiency in B-cell malignancies and autoimmune diseases." (PMID 33122850, 2021). "BTK inhibitors have been noted as treatment drugs for these diseases, exhibiting an outstandingly effective therapeutic effect that is increased through BTK inhibition in an experimental animal model for autoimmune disease or B-cell malignancy." (PMID 32357562, 2020). "Second-generation irreversible BTK inhibitors are currently in clinical trials and are being developed for the treatment of patients with autoimmune disorders and B cell malignancies." (PMID 33113810, 2020). "Bruton’s tyrosine kinase (BTK) is an attractive target for treating patients with B cell malignancies and autoimmune diseases." (PMID 33113810, 2020). "This is of interest by itself, as in other well characterized, B-cell-driven autoimmune diseases, such as anti-citrullinated protein antibody-positive RA, expression of BTK in B cells was increased." (PMID 32761407, 2020). "Ibrutinib, as a classical BTK inhibitor, makes it a uniquely attractive target for a safe and efficacious treatment of autoimmune diseases especially in CLL patients." (PMID 33004832, 2020). "Small-molecule BTK inhibitors have been proven effective in the treatment of autoimmune diseases in preclinical studies." (PMID 31651327, 2019).
autoimmune disease (continued). "Bruton’s tyrosine kinase (BTK) regulates critical signal transduction pathways involved in the pathobiology of rheumatoid arthritis (RA) and other autoimmune disorders." (PMID 28742141, 2017). "BTK is a key intracellular enzyme that regulates critical pathways involved in the pathobiology of RA and other autoimmune disorders." (PMID 28742141, 2017). "Overall, it appears that BTK is an attractive novel therapeutic target for RA and other autoimmune diseases." (PMID 28265691, 2017). "Due to its high selectivity, potency and safety, CHMFL-BTK-11 will be a preferred pharmacological tool for dissection of BTK mediated signaling pathway in the autoimmune diseases and a variety of cancers." (PMID 28352114, 2017). "Inhibition of BTK is emerging as a promising target for B-cell malignancies, other cancers with BTK over-expression, and certain autoimmune diseases where BTK is involved." (PMID 24759210, 2014). "Ibrutinib, a novel BTK-targeting inhibitor, has shown significant activities across a variety of B-cell neoplastic disorders and autoimmune diseases in preclinical models and clinical trials." (PMID 23958373, 2013). "and 3) Preclinical models and clinical experiences with ibrutinib and other BTK inhibitors in the treatment of various B-cell disorders and autoimmune disorders." (PMID 23958373, 2013). "We next investigated if BTK was required for the TLR9 and BCR synergy as the inhibitor is of interest in SLE therapy and TLR9 is linked to the progression of this autoimmune disease." (PMID 23967355, 2013). "Small molecules with BTK-inhibitory property have emerged as promising therapeutic agents for the treatment of hematological malignancies and autoimmune disorders." (PMID 23958373, 2013). "Bruton's tyrosine kinase (BTK) has emerged as a promising target for autoimmune disorders." (PMID 39973148, 2025). "Indeed, studies have shown increased levels of BTK expression in B cells from patients suffering from autoimmune diseases, which appears to be correlated with autoantibody production." (PMID 38698867, 2024). "Current evidence suggests that targeting BTK could be a promising therapeutic option for autoimmune diseases such as RA due to the regulation of B-cell proliferation and function." (PMID 36821545, 2023). "The observed effectiveness, in both animal models and human subjects, of BTK inhibitors in several autoimmune diseases further strengthens the hypothesis that regulation of this cascade might be of therapeutic value." (PMID 36826039, 2023). "In several autoimmune diseases, BTK activity is enhanced in peripheral blood B cells." (PMID 38129902, 2023). "Aberrant BTK expression is evident in B-cell malignancies and autoimmune diseases." (PMID 36986499, 2023). "Thus, BTK is a promising therapeutic molecular target for treating autoimmune diseases such as RA and systemic lupus erythematosus." (PMID 36821545, 2023). "The review consists of eight sections; Section 2, Section 3, Section 4, Section 5, Section 6 and Section 7 which brief the role of BTK in BCR signaling, its association with different malignancies and autoimmune diseases, and the approval status and chemistry of covalent and non-covalent inhibitors." (PMID 36986499, 2023). "Various BTK inhibitors have demonstrated anti-inflammatory effects by inhibiting the functions of immune cells in preclinical experimental models; these inhibitors are under clinical development for the treatment of autoimmune diseases." (PMID 36821545, 2023). "BTK inhibition is vital to halt B-cell malignancies and autoimmune diseases." (PMID 36986499, 2023). "This review aims to explore the conformational changes of BTK and its intermolecular interactions with inhibitor drugs to reveal the structural complementarity, in addition to outlining the signal transduction and BTK’s role in B-cell malignancies and autoimmune diseases." (PMID 36986499, 2023).